ACE (angiotensin I converting enzyme)
Diseases named in the same sentence as ACE in open-access papers (continued):
Sharing a sentence is not in itself a finding about the gene and the disease.
diabetes (continued). "Further to this, the use of ACE inhibitors and ARBs has been widely advocated as pharmacologic prevention and treatment of CKD in patients with diabetes, particularly in the presence of albuminuria." (PMID 29949629, 2018). "So we should take caution in combining aliskiren with an ACE inhibitor or an ARB, particularly in patients with heart disease, CKD and diabetes mellitus." (PMID 29179525, 2017). "Inhibition of angiotensin-converting enzyme (ACE), and thereby antagonizing the RAS, has been shown to improve glucose homeostasis and, albeit inconsistently, to reduce incidence of type 2 diabetes mellitus in large-scale clinical trials." (PMID 28835639, 2017). "We also analyzed the effect of diabetes on ACE2 and ACE modifications in tissues from NOD diabetic mice as compared to non-obese resistant (NOR) mice." (PMID 28273875, 2017). "In adults with diabetes, comparisons of different RAS blockers showed similar effects of ACE inhibitors and ARBs on major cardiovascular and renal outcomes." (PMID 26954482, 2016). "Consistent with this view, ACE inhibitors and angiotensin II receptor blockers represent the first line therapy for primary and secondary CVD prevention in patients with diabetes." (PMID 27652272, 2016). "Consistently, the results of a recent meta-analysis showing that dual RAS blockade with ACE inhibition and ARB is the most effective strategy to prevent end-stage renal disease in patients with diabetes and kidney disease." (PMID 27471550, 2016). "Today, ACE inhibitors and angiotensin II receptor blockers represent the first line therapy for primary and secondary CVD prevention in patients with diabetes." (PMID 27652272, 2016). "During the 24-month follow-up, 51.4% of the initiators of other drugs purchased ACE inhibitors/ARB inhibitors, 33.4% beta blockers, 17.9% diabetes drugs, and 17.3% nitrates." (PMID 25658919, 2015). "ACE inhibitors and AT1 blockers are effective in reducing Ang-II–mediated inflammation and end-organ damage in animals with diabetes." (PMID 23690953, 2013). "FGF-23 was inversely associated with EF after multivariate adjustment for age, race, gender, diabetes, eGFR, serum C-reactive protein concentrations, LVH, and the use of β-blockers and ACE inhibitors (β –2.03; p = 0.004)." (PMID 23849306, 2013). "Ang II and angiotensin converting enzyme (ACE) are activated in type 2 diabetes, and are involved in the development of microvascular and macrovascular complications of diabetes such as nephropathy, retinopathy and cardiovascular disease." (PMID 23646149, 2013). "With regard to insufficient RAS blockade by ACE inhibitors and ARBs, we described an intracellular cardiac RAS that is significantly upregulated in diabetes." (PMID 24215514, 2013). "However, diabetes did not associate with increased urinary ACE activity or ACE protein." (PMID 22629438, 2012). "Patients with diabetes were more likely to receive drugs acting on the renin-angiotensin system (RAS blockade), either an ACE-inhibitor or an angiotensin receptor blocker, either at baseline or at some time during the study." (PMID 21274458, 2011). "For the study, INVEST randomly assigned 6 400 patients with diabetes and CAD to blood pressure-lowering therapy based on either a calcium channel blocker or a beta-blocker, plus an angiotensin converting enzyme (ACE) inhibitor and/ or a thiazide diuretic." (PMID 20532441, 2010). "In a retrospective cohort study of 3,998 patients with diabetes and IHD, we evaluated use of ACE inhibitors or angiotensin receptor blockers, β-blockers, and statin medications." (PMID 17173679, 2006). "Our main focus was on class I indicated medications, including ACE-inhibitors, β-blockers, and statin, for patients with CAD and diabetes." (PMID 17173679, 2006). "In clinical trials, both statin and ACE-inhibitor medications have been shown to benefit patients with IHD, diabetes or both of these conditions)." (PMID 17173679, 2006).
diabetes (continued). "Systemically, all diabetic animals, irrespective of treatment, exhibited increased ACE and ACE2 activity, confirming previous reports that diabetes is associated with dysregulation of the RAAS." (PMID 40650071, 2025). "Although angiotensin-converting enzyme (ACE) inhibitors and angiotensin receptor blockers (ARBs) are theoretically beneficial for controlling diabetes in patients with COVID-19 infection, this is not supported by experimental data." (PMID 40950999, 2025). "Altogether, these results indicate that extracellular ACE activation and ATII production, most probably by cardiac fibroblasts, play an important role in diabetes-induced alterations of Ca2+i homeostasis and, consequently, contractile performance of the isolated rat heart." (PMID 40149735, 2025). "Our model incorporates nine predictive factors: age, drinking history, diabetes, angina pectoris, cerebrovascular disease history, intraoperative MAP ≤60 mmHg for 5–10 min, preoperative blood sodium level, preoperative ACE inhibitor use, and perioperative NSAID use." (PMID 40809288, 2025). "ACE inhibitor (BF = 0.5455): potential usefulness in regulating blood pressure and cardiovascular health; DPP-IV inhibitor (BF = 0.4545): possible role in metabolic regulation and diabetes management." (PMID 40724906, 2025). "Similarly, ACE inhibition and statin therapy can positively affect EPC amounts and function in adults with diabetes." (PMID 40710348, 2025). "Routine use of ACE inhibitors in the absence of clear indications (e.g., reducedLVEF, recent MI, diabetes, or CKD) is discouraged early postoperatively due topotential hypotension and variable BP responses." (PMID 41356289, 2025). "It was concluded that this ACE inhibitor has an antioxidant effect and can prevent STZ diabetes-induced nephropathy through amelioration of the glycemic state and antioxidant defense system together with the suppression of oxidative stress, inflammation, and apoptosis." (PMID 40699692, 2025). "Among patients with diabetes with proteinuria, for non-pregnant women, 192 physicians prescribe an ACE inhibitor, which is good practice and recommended for patients with proteinuria to prevent the progression of diabetic kidney disease." (PMID 38541098, 2024). "Our review highlights strong evidence of a protective role of antihypertensive drugs, specifically ACE inhibitors and CCBs, in CHD, stroke, post-stroke functional outcomes, diabetes, and kidney function, which is supported by evidence from RCTs, as well as national and international guidelines." (PMID 39567981, 2024). "The ESC guidelines recommend anti-aldosterone medication in patients with a history of myocardial infarction, with EF ≤40%, with heart failure or diabetes, and without renal failure or hyperkalemia, along with treatment with ACE inhibitors and beta-blockers." (PMID 39062156, 2024). "During diabetes, the intrarenal renin–angiotensin system (RAS) is inappropriately activated as reflected in the stimulation of intrarenal renin and prorenin synthesis, angiotensin-converting enzyme (ACE), and intratubular levels of angiotensinogen (AGT)." (PMID 38203807, 2024). "First, those with diabetes were less likely to undergo invasive investigation with ICA or revascularisation but were more likely to receive guideline-directed medical therapy including statins, β-blockers and ACE inhibitors." (PMID 39358593, 2024). "Those with diabetes were also more likely than those without diabetes to receive statins (89% vs 82%, p<0.001), ACE inhibitors/ARBs (78% vs 72%, p<0.001) and β-blockers (74% vs 71%, p<0.001)." (PMID 39358593, 2024). "There is clear evidence that angiotensin-converting enzyme (ACE)-inhibitors and angiotensin-receptor blockers (ARBs) appear to be more effective than atenolol in terms of microvascular protection also in patients with diabetes mellitus." (PMID 37568294, 2023).
diabetes (continued). "Other variables with a p value under 0.20 in the univariate analysis and which were included in the multivariate analysis were CD cardiac form, sex, body mass index, diabetes mellitus, LV aneurysm, MMP-9, use of either ACE inhibitor or ARB, use of warfarin, and use of amiodarone." (PMID 38126526, 2023). "The present study aimed to evaluate the protective effects of enalapril (an ACE inhibitor) and paricalcitol (a vitamin D analog), individually or in combination, on streptozotocin (STZ)-diabetes-induced testicular dysfunction in rats and to identify the possible mechanisms for this protection." (PMID 38133142, 2023). "No changes in use of opioids, ACE inhibitors/sartans, beta blockers, loop diuretics, oral anticoagulants, or medicines for osteoporosis, diabetes or the cognitive symptoms of dementia were observed post-RMMR." (PMID 35676644, 2022). "ACE played a role in vasoconstriction and fibrosis by binding to AT1, resulting in a significant reduction in insulin secretion, inducing and aggravating diabetes." (PMID 36699034, 2022). "The mean serum ACE (92.35±10.28), oxLDL (48.59±8.56), hs-CRP (5.87±1.62), MMP-9 (89.20±30.19), and MDA (1.146±0.198) levels were significantly (p-value <0.0001) higher in smokers with CHD and diabetes (group 3) when compared to group 1 and group 2." (PMID 36110446, 2022). "The action of ACE and ACE2 in the kidneys may determine a decline in glomerular filtration rate at advanced stages of diabetes mellitus." (PMID 35176079, 2022). "More CKD patients with diabetes versus those without diabetes had their albumin-to-creatinine ratio (ACR) assessed (64.2 vs. 17.0%) or received an ACE inhibitor/ARB (78.3 vs. 58.1%) or statins (64.6 vs. 39.2%)." (PMID 35583597, 2022). "This, for example, is the case in T2D, where a negative correlation between ACE2/ACE vs. HbA1C is observed and loss of ACE2 exacerbates cardiovascular complications in Diabetes." (PMID 39086962, 2022). "In line with this, other studies have shown that people both with and without diabetes but treated with an ACE inhibitor or ARB have reduced cfPWV." (PMID 35978373, 2022). "Angiotensin-converting enzyme (ACE) inhibitors and angiotensin receptor blockers (ARB) are widely used due to their well-established benefit in coronary artery disease and renal protection in diabetes mellitus." (PMID 33628676, 2021). "However, in another study in STZ-induced diabetes and renal dysfunction in rats, ACE2 mRNA increased, but to a lesser extent than ACE, suggesting the predominance of the ACE/Ang II/AT1R axis." (PMID 33805760, 2021). "ACE2 is an important component of RAAS, may be equally or even more important than ACE in regulating the cardiac balance of the RAAS, particularly in the setting of diabetes." (PMID 33602129, 2021). "In a number of these studies, ACE inhibitors were shown to provide renal protection in Bergamo Nephrologic Diabetes Complication Trials (BENEDICT) and ADVANCE (Action in Diabetes and Vascular Disease: Preterax and Diamicron MR Controlled Evaluation) studies." (PMID 33507688, 2021). "Angiotensin-converting enzyme (ACE) inhibitors (ACEIs) and AT1 receptor antagonists (ARBs) are the first-line drugs to reduce the progression of end-stage renal disease in patients with diabetes." (PMID 33995063, 2021). "A meta-analysis compared studies that used ACE inhibitors or ARBs and found that the former was more effective in improving IS in hypertensive patients without diabetes." (PMID 34234365, 2021). "ACE inhibitors and angiotensin-receptor blockers (ARBs), which are used to balance blood pressure and vascular complications in chronic diseases (e.g. cardiovascular diseases and diabetes), provide various clinical benefits by increasing the expression of ACE2 while blocking ACE." (PMID 33414783, 2020). "But also the use of ß-blockers (82.7% vs. 77.5%), ACE inhibitors and angiotensin receptor blockers (80.3% vs. 77.4%) was higher in the diabetes group compared to non-diabetics." (PMID 32525964, 2020).
diabetes (continued). "Additional analyses did neither result in a significant confounding effect of β‐blocker usage, ADP receptor antagonists, statins, ACE inhibitors, nor of diabetes." (PMID 31074520, 2019). "Indeed, women with diabetes or CVD are diagnosed later and have a lower frequency of statin therapy, aspirin use, and ACE inhibitor and β-blocker use than men." (PMID 31296205, 2019). "In Canada, diabetes practice guidelines recommend antidiabetic agents (including insulin) and cardioprotective therapies (antihypertensives, notably ACE inhibitors and angiotensin-receptor blockers (ARB), and lipid-lowering agents, notably statins) for individuals aged ≥55 with diabetes." (PMID 31805662, 2019). "Patients with LLA had lower rates of statins, antiplatelet therapy, ACE inhibitors and Angiotensin Receptor Blockers, metformin and insulin prescriptions at baseline compared to those without diabetes-related LLA (p < 0.001)." (PMID 30823912, 2019). "Only ARBs or ACE inhibitors are recommended for first-line treatment in patients with diabetes mellitus and CKD (with proteinuria), whereas CCBs are not recommended." (PMID 30842611, 2019). "FPG levels were significantly higher in those using ACE inhibitors compared to diuretics (P=0.01), even when analysis was restricted to individuals with diabetes (data not shown, P=0.007)." (PMID 30364090, 2018). "This study aimed to evaluate the frequencies of the angiotensin converting enzyme (ACE) gene insertion/deletion (I/D) and methylenetetrahydrofolate reductase (MTHFR) gene C677T polymorphisms in obese patients with and without type 2 diabetes mellitus (T2DM)." (PMID 29694640, 2018). "Effect of training group, time point (TP), age, diabetes duration, ACE inhibitors, use of non-ACE inhibitors, statin use, and those study participants that commenced the study during the extended enrolment period on HbA1c." (PMID 30210450, 2018). "In a randomized comparator study including patients with diabetes (n = 24) CFVR assessed by TTDE improved in the group treated with ACE inhibitor, but the effect was not compared with placebo." (PMID 29883497, 2018). "AEA responses were not altered in patients with diabetes, cancer, or hypercholesterolaemia or in patients taking ACE inhibitors, hypoglycaemic agents, NSAIDS, beta-blockers (data not shown) or statins." (PMID 27633407, 2016). "In patients without diabetes mellitus, a benefit on pneumonia rates was seen with both ACE inhibitors (adjusted OR 0.67, 95% CI 0.50 to.89) and ARBs (adjusted OR 0.49, 95% CI 0.32 to 0.75)." (PMID 25353172, 2014). "The Asia Pacific Cohort Studies Collaboration (APCSC) study indicated that major CV risk was reduced to a comparable extent in hypertensive individuals with or without diabetes while on an ACE inhibitor-based treatment, or other antihypertensive regimens." (PMID 25344747, 2014). "The use of ACE inhibitors and AT1 and/or AT2 receptor blockers have shown preliminary experimental promise in the treatment of stress, depression, alcohol consumption, seizure, AD, PD, and diabetes." (PMID 24298267, 2013). "It was found that the use of a new class of antihypertensive drugs, angiotensin II receptor antagonists and ACE inhibitors was more common among people with diabetes compared to people without diabetes." (PMID 23837500, 2013). "Angiotensin-converting enzyme (ACE) inhibitors (or angiotensin type II receptor blockers (ARBs)) should be used in hypertensive patients with CAD with or without diabetes, as well as in patients with left ventricular dysfunction." (PMID 23369274, 2012). "Also in type 2 diabetic rats, blockade of Ang II activity by ACE inhibitors and ARBs ameliorated progression of proteinuria and preserved glomerular structure further supporting RAS activation in diabetes." (PMID 21915376, 2011).
diabetes (continued). "In fact, IOP before the clamp procedure was higher in the diabetes group, compared to the control group, suggesting that the ACE inhibitors were not prescribed at a dose sufficient to maintain IOP within normal levels." (PMID 20573241, 2010). "The results showed that hazard ratios for diabetes mellitus, 4G/4G of PAI-1 gene and DD of ACE gene were high and statistically significant, p = 0.003, p = 0.009, p = 0.005, respectively, these three factors were the independent prognostic factors for MACE in CAD patients." (PMID 28352370, 2010). "Other predictors of mortality include increased age, ICD type, diabetes mellitus, absence of beta blocker, and absence of ACE inhibitors/ARBs." (PMID 20811610, 2010). "Studies that have focused on the effects of antiatherogenic effect of ACE inhibitors on diabetes are scarce and no research was done to examine the effect of ramipril on arterial stiffness in IGT patients." (PMID 20165647, 2009). "This raises the possibility that, in diabetes, increased ACE activity with balanced domain interaction—rather than N-domain dominance—could help protect tissues." (PMID 40650071, 2025). "The pooled analysis using a random-effect model showed thatperioperative use of ACE inhibitors does not significantly impact SHG in patientswithout diabetes after cardiac surgery, with no statistically significantdifference [WMD = 1.58, 95% CI (0.74, 3.38), Z = 1.19, p = 0.23]." (PMID 39867189, 2025). "Angiotensin converting enzyme (ACE) inhibitor (BF = 0.4286): potential role in blood pressure regulation and cardiovascular protection; dipeptidyl peptidase (DPP)-IV inhibitor (BF = 0.6429): possible application in diabetes management by enhancing insulin regulation." (PMID 40724906, 2025). "The TRANSCEND study (Telmisartan Randomized Assessment Study in ACE-I Intolerant Subjects with Cardiovascular Disease) evaluated the role of telmisartan in patients diagnosed with ischemic heart disease or diabetes with organ damage, who did not tolerate ACE inhibitors." (PMID 39062156, 2024). "However, some studies failed to discern any relationship between the ACE gene polymorphism and CAD in patients with diabetes." (PMID 35741131, 2022). "Mungbean has been reported for its biological activities, including angiotensin I-converting enzyme (ACE) inhibition, efficiency to reduce lipid accumulation and inflammation, anti-formation of advanced glycation end products (AGEs), and anti-diabetes activities." (PMID 33800074, 2021). "In patients with diabetes being treated with an ACE inhibitor, ARB, or spironolactone, compared with no monitoring, regular monitoring of serum potassium has been shown to decrease the risk of hyperkalemia-related adverse events (adjusted relative risk 0.5, 95% CI 0.37–0.66)." (PMID 33214722, 2021). "Angiotensin-converting enzyme (ACE) inhibitors and angiotensin receptor blockers (ARB) are widely used for their well-established benefit in reducing morbidity and mortality in patients with coronary artery disease and for renal protection in patients with diabetes mellitus." (PMID 33628676, 2021). "However, elevated ACE levels may also be found in other granulomatous disorders such as chronic beryllium disease (CBD) or leprosy, as well as in liver disease, lymphoma, diabetes and hyperthyroidism." (PMID 34573900, 2021). "The basis of Fang and colleagues’ hypothesis is as follows: (a) increase in ACE2 activity in cardiovascular diseases (also in other diseases, e.g., diabetes) and (b) increase in ACE2 activity in experimental models under the influence of ACE inhibitors and angiotensin 2 receptor blockers." (PMID 33925881, 2021). "Whilst a number of agents can ameliorate (e.g. angiotensin converting enzyme [ACE] inhibitors, perhexiline, statins and insulin) or circumvent (e.g. nitrite and sGC activators) NO• resistance, nitroxyl (HNO) donors offer a novel opportunity to circumvent NO• resistance in diabetes." (PMID 32508651, 2020).